PTPN20 (protein tyrosine phosphatase non-receptor type 20)
Description:
Tyrosine-protein phosphatase targeted to sites of actin polymerization in response of varied extracellular stimuli. Has tyrosine phosphatase activity towards various tyrosyl phosphorylated substrates.
Synonyms: PTPN20A; PTPN20B; bA42B19.1; DKFZP566K0524; bA142I17.1; CT126
Tractability: No criterion of Open Targets' tractability assessment is met for any kind of drug.
Gene: Protein-coding gene on chromosome 10 (46,911,396 to 47,002,488, forward strand). Ensembl gene ENSG00000204179.
Subcellular location: Nucleus; Cytoplasm; Cytoplasm, cytoskeleton, microtubule organizing center, centrosome
Subcellular location (Human Protein Atlas): Centriolar satellite
Pathways (Reactome):
Immune System: Interleukin-37 signaling
Gene Ontology:
Molecular function: protein tyrosine phosphatase activity
Cellular component: centriolar satellite; nucleoplasm; centrosome; cytoplasm; nucleus
Genetic constraint (gnomAD): Loss-of-function variants: 9 observed, 22.49 expected, observed/expected ratio (o/e) 0.4, 90% interval 0.24 to 0.7. The synonymous counts are far from expectation, so gnomAD's model fits this gene poorly and the ratio says little. Missense variants: 107 observed, 212.72 expected, observed/expected ratio (o/e) 0.5, 90% interval 0.43 to 0.59. Synonymous variants: 32 observed, 66.21 expected, observed/expected ratio (o/e) 0.48, 90% interval 0.36 to 0.65.
Homologues: Orthologues: chimpanzee PTPN20 (99% identical), macaque PTPN20 (94% identical), pig PTPN20 (67% identical), rat Ptpn20 (66% identical), mouse Ptpn20 (65% identical), dog PTPN20 (60% identical), tropical clawed frog frmpd2 (38% identical), zebrafish ptpn20 (18% identical). Paralogues in human: PTPN13 (31% identical), PTPRS (28% identical), PTPRD (28% identical), PTPRZ1 (27% identical), PTPRG (27% identical), PTPRB (27% identical), PTPRF (27% identical), PTPRK (26% identical), PTPRM (26% identical), PTPRJ (26% identical), PTPN11 (25% identical), PTPRT (25% identical), and 23 more.
Diseases named in the same sentence as PTPN20 in open-access papers:
PTPN20 is named in the same sentence as 22 diseases in open-access papers, as found by Europe PMC text mining. Sharing a sentence is not in itself a finding about the gene and the disease. The quoted sentences say what the papers report.
Hydrocephalus (3 papers, 2022 to 2024). Hydrocephalus is an active distension of the ventricular system of the brain resulting from inadequate passage of CSF from its point of production within the cerebral ventricles to its point of absorption into the systemic circulation. "PTPN20 deletion in the choroid plexus epithelium was shown to cause an overproduction of cerebrospinal fluid, contributing to the formation of hydrocephalus." (PMID 38674024, 2024). "Our strategy of identifying potential pathogenic genes in hydrocephalic H-Tx rats and elucidating mechanisms in transgenic mouse models revealed the unexpected pathological relevance of hydrocephalus to Ptpn20 deficiency." (PMID 35658898, 2022). "This study determined the chromosomal location of the hydrocephalus-associated Ptpn20 gene in hydrocephalic H-Tx rats." (PMID 35658898, 2022). "To investigate whether deletion of Ptpn20 represents a risk factor for hydrocephalus, we generated Ptpn20-knockout (Ptpn20−/−) mice using CRISPR/Cas9 technology." (PMID 35658898, 2022). "We then generated Ptpn20-deficient mice to investigate whether the deletion of Ptpn20 is a risk for hydrocephalus." (PMID 35658898, 2022). "Ptpn20 makes a substantial contribution to CSF production and provides a novel approach for diagnosing hydrocephalus." (PMID 35658898, 2022). "An experimental study of genetic risk for hydrocephalus revealed that loss of the Ptpn20 gene in H-TX rats resulted in the development of communicating hydrocephalus, and the same result was observed in Ptpn20−/− mice, in which NKCC1 phosphorylation is maintained in choroid plexus epithelial cells." (PMID 39839745, 2024). "However, further analysis in adult Ptpn20−/− mice revealed ventriculomegaly in more than half of these mice without significant blockage of CSF circulatory pathways, thus indicating that Ptpn20−/− mice had developed communicating hydrocephalus." (PMID 35658898, 2022). "To establish whether an anatomical defect resulted in hydrocephalus, we injected Evans blue in the lateral ventricle of Ptpn20−/− mice." (PMID 35658898, 2022). "The high level of pNKCC1 mediated by Ptpn20 deletion in CP epithelium may cause overproduction of cerebrospinal fluid and contribute to the formation of hydrocephalus in Ptpn20−/− mice." (PMID 35658898, 2022). "Ptpn20 may be a potential therapeutic target in the treatment of hydrocephalus." (PMID 35658898, 2022). "In Ptpn20−/− mice, VBR exceeding the mean WT value by 2 standard deviations was defined as indicating hydrocephalus." (PMID 35658898, 2022). "Of these 29 Ptpn20−/− mice, 16 mice met the criteria for hydrocephalus, and 13 mice did not develop hydrocephalus, while some of the hydrocephalic mice exhibited very mild ventriculomegaly." (PMID 35658898, 2022).
esophageal carcinoma (2 papers, 2020 to 2023). A primary or metastatic malignant neoplasm involving the esophagus. "In esophageal carcinoma, PTPN20 was upregulated and associated with both the TNM stage and N stage." (PMID 37359510, 2023). "For esophageal carcinoma (ESCA), PTPN1 and PTPN12 levels were correlated with incidence; PTPN20 was associated with poor prognosis." (PMID 32536826, 2020). "Importantly, high levels of PTPN20 predicted poor survival in esophageal carcinoma patients, indicating that PTPN20 levels may also have prognostic value in certain cancer types." (PMID 37359510, 2023).
gastric cancer (2 papers, 2023 to 2024). A primary or metastatic malignant neoplasm involving the stomach. "Together, we have identified a differentially expressed, innate-immunity associated PTPN20 gene, which has prognostic value in gastric cancer." (PMID 37359510, 2023). "PTPN20 was identified as an innate immunity-related gene in gastric cancer with Helicobacter pylori infection." (PMID 38674024, 2024).
acute myeloid leukemia (1 paper, 2023). Acute myeloid leukemia (AML) is a group of neoplasms arising from precursor cells committed to the myeloid cell-line differentiation. "Specifically, while the expression of PTPN20 was reduced in colorectal cancer, PTPN20 levels showed no change between acute myeloid leukemia cell and normal cells." (PMID 37359510, 2023).
bladder cancer (1 paper, 2023). "utilized gene expression profiling and real-time PCR to identify possible cancer-testis antigens and found PTPN20 was a promising candidate in multiple myeloma and bladder cancer." (PMID 37359510, 2023).
breast carcinoma (1 paper, 2023). "They uncovered that the expression of PTPN20, PTPN7, and several other PTPs were significantly augmented in breast cancer tissues compared to normal tissues and identified a strong correlation between PTPN7 expression and immune infiltration." (PMID 37359510, 2023).
congenital hydrocephalus (1 paper, 2022). Hydrocephalus that is present at birth. "Ptpn20−/− mice did not exhibit the characteristics of congenital hydrocephalus observed in H-Tx rats after birth." (PMID 35658898, 2022).
COVID-19 (1 paper, 2024). A disease caused by infection with severe acute respiratory syndrome coronavirus 2. "PTPN20 was among the top-10 proteins with the highest mean autoantibody response in COVID-19 patients." (PMID 38674024, 2024).
Ewing sarcoma (1 paper, 2023). A small round cell tumor that lacks morphologic, immunohistochemical, and electron microscopic evidence of neuroectodermal differentiation. "They revealed that PTPN20 may play a role in Ewing sarcoma (ES)/primitive neuroectodermal tumor (PNET) as its gene locus underwent deletion in some ES/PNET samples." (PMID 37359510, 2023).
hepatocellular carcinoma (1 paper, 2023). A malignant tumor that arises from hepatocytes. "In hepatocellular carcinoma (HCC), PTPN20 may act as an inhibitor for the STAT3 signaling pathway." (PMID 37359510, 2023).
melanoma (1 paper, 2023). A malignant, usually aggressive tumor composed of atypical, neoplastic melanocytes. "In addition, we found associations between MITF targeting and PTPN20, a tyrosine phosphatase coding gene, providing further evidence that disrupted signaling mediated by MITF regulation plays an important role in melanoma." (PMID 36894939, 2023).
multiple myeloma (1 paper, 2023). "Similarly, another group found PTPN20 to be a marker for multiple myeloma by using a self-training subspace clustering (SSC)-low-rank representation (LRR) algorithm." (PMID 37359510, 2023).
peripheral arterial occlusive disease (1 paper, 2023). "In peripheral arterial occlusive disease, PTPN20 was found to be downregulated in intermediate lesions when compared to normal femoral arteries, indicating that restoring PTPN20 may improve peripheral arterial occlusive disease." (PMID 37359510, 2023).
cancer (2 papers, 2023). A tumor composed of atypical neoplastic, often pleomorphic cells that invade other tissues. "Somatic mutation data was analyzed and visualized in the PTPN20 high and low expression groups because TMB has been linked to immunotherapeutic response and prognosis in cancer." (PMID 37359510, 2023). "PTPN20 has been shown to have differential expression across cancer types, suggesting that it may have distinct roles in different cancer types." (PMID 37359510, 2023). "To summarize, our findings support the hypothesis that PTPN20 plays a critical role in cancer progression and may serve as a prognostic biomarker for Hp-related GC patients." (PMID 37359510, 2023). "Moreover, PTPN20 can also function as cancer marker or antigen." (PMID 37359510, 2023). "The CNV percentage in pan-cancer indicated that heterozygous amplification in cancers were widely found in genes PTPN1, PTPN7, PTPN12 and PTPN14 in most cancers, while heterozygous deletions were widely found in genes PTPN13, PTPN20, PTPN22 and PTPN23." (PMID 37884566, 2023).
tumor (2 papers, 2022 to 2023). "Additionally, PTPN20 and its related gene set was found to be associated with several critical characteristics of GC, such as immune cell functions and tumor mutation burden." (PMID 37359510, 2023). "In addition, PTPN20 is associated with immune cell infiltration and tumor mutation burden in these GC patients." (PMID 37359510, 2023). "We analyzed the expression levels of PTPNs in the TCGA database and discovered that PTPN1, PTPN6, PTPN7, PTPN18, PTPN20, and PTPN22 were significantly upregulated in tumor samples, while PTPN4, PTPN5, PTPN10, PTPN11, PTPN13, PTPN14, and PTPN21 were downregulated in tumor samples." (PMID 36226189, 2022).
PTPN20 also shares sentences with these, for which no sentence is quoted: communicating hydrocephalus (2 papers); Aqueductal stenosis (1); colorectal cancer (1); leukemia (1); Pancreatic Cancer (1); primitive neuroectodermal tumor (1); Ventriculomegaly (1).